EZH2 (enhancer of zeste 2 polycomb repressive complex 2 subunit)
Diseases named in the same sentence as EZH2 in open-access papers (continued):
Sharing a sentence is not in itself a finding about the gene and the disease.
tumor (continued). "EZH2 knockdown by RNA interference in MPNST cell lines induces MPNST cell apoptosis in vitro and inhibits MPNST tumor growth in vivo, suggesting that EZH2 is a potential therapeutic target in MPNST." (PMID 25890085, 2015). "Our previous studies demonstrated that EZH2 was overexpressed in NPC cell lines and tissues, which promoted tumor growth and metastasis in vitro and in vivo." (PMID 25237831, 2014). "It is well established that G9a- and EZH2-mediated histone H3K9 and H3K27 hypermethylation contributes to the epigenetic silencing of tumor suppressor genes." (PMID 24652950, 2014). "In conclusion, EZH2 inhibitors such as SAHA and DZNep exert multiple anticancer effects through activation of tumor-suppressor miRNAs in human cancer cells." (PMID 24861464, 2014). "Moreover, a recent report indicates that the RD cell line, derived from an embryonal RMS local recurrence and thus representative of an aggressive tumor, may reactivate muscle-specific genes and develop a partial recovery of myocyte phenotype following EZH2 knockdown when depleted of serum." (PMID 24575771, 2014). "Several reports have noted that EZH2 was over-expressed in most HCC resection tissues by immunohistochemistry, whereas it was negatively expressed in nearly all of the corresponding non-tumor tissues, which was consistent with our findings." (PMID 25226601, 2014). "Nuclear expression of all individual markers (EZH2, BMI1, SUZ12 and H3K27me3) in tumor tissues was compared to nuclear expression in paired normal colorectal tissues." (PMID 25243792, 2014). "Among these, we validated EZH2, MCL-1 and FOS as direct targets of miR-101 and silencing of these genes mimics the tumor suppressive effects observed on promoting microRNA-101 function." (PMID 25153722, 2014). "Thus, the pRB/E2F/EZH2 pathway may be one of the mechanisms involved in tumor response to CRT." (PMID 25159232, 2014). "Enhancer of Zeste Homolog 2 (EZH2) is the catalytic subunit of Polycomb repressive complex 2 (PRC2), which methylates histone H3 lysine 27, thereby silencing multiple tumor suppressor genes." (PMID 25237831, 2014). "The CD44hi cells from the M-1 tumor exhibited a more primitive phenotype (in terms of expected BMI, hTERT, SUZ12, EZH2, OCT-4 expression), as compared to the CD44hi cells from the M-2 sample (with only higher hTERT expression)." (PMID 24019906, 2013). "This interaction contributes to the role of CBX in promoting EZH2-mediated H3-K27 methylation at the INK4b/ARF/INK4a locus and consequently represses the tumor suppresser INK4a gene." (PMID 24013378, 2013). "It is known that polycomb proteins play crucial roles in aggressive tumor growth and cancer stem cell maintenance, and that the EPC1-E2F6 complex interacts with EZH2 to contribute to cell proliferation." (PMID 23469177, 2013). "Taken together, our study has shed mechanistic insight into EZH2-H3K27me3 epigenetic repression of DLC1 and advocated the significant pro-metastatic role of EZH2 via repressing tumor and metastasis suppressors." (PMID 23826380, 2013). "EZH2 was found to be upregulated by oncogenic RAS through MEK-ERK signaling, leading to the downregulation of tumor suppressors such as RUNX3 and p27(Kip1)." (PMID 23940717, 2013). "Further studies are warranted to examine the effects of these specific inhibitors of EZH2 on the characteristics of IBC, such as homotypic aggregation of tumor emboli, invasion and metastasis of IBCs." (PMID 24294976, 2013). "To explore mechanisms driving EZH2 activation and to confirm the oncogenic role of EZH2 in SCLC, we studied copy number profiles of 14 SCLC tumours and 14 SCLC cell lines and assessed cell viability after EZH2 knockdown." (PMID 23967231, 2013). "Nevertheless, its current potential for reducing EZH2 levels, reverting epithelial-to-mesenchymal transition (EMT), and preventing tumor progression, makes it a highly promising antimetastatic agent." (PMID 23940717, 2013).
tumor (continued). "EZH2 is a newly identified downstream target of E2F1, which is a major downstream effector of the RB tumor suppressor and has a pivotal role in controlling cell cycle progression." (PMID 22970185, 2012). "In the present study, we detected EZH2 protein and mRNA expression in ESCC tumor tissues and matched normal tissues by western blot and qRT-PCR." (PMID 22867052, 2012). "We validated the expression of EZH2 and its binding partner EED in purified tumor cells from 8 paired primary tumor and lymph node samples with real-time PCR." (PMID 23251464, 2012). "Multivariate Cox regression analysis indicated that tumor recurrence, low-level of miR-214 and CDH1, and high-level of EZH2 and CTNNB1 were prognostic factors for early HCC recurrence and poor survival." (PMID 22962603, 2012). "Together, these data add mechanistic insight to prior observations of increased EZH2 expression and decreased CIITA expression in multiple tumor types." (PMID 22563434, 2012). "Pharmacologic inhibition of EZH2, an emerging therapeutic strategy, impairs both TSC self-renewal and speed of tumor formation." (PMID 24212632, 2011). "MAGE-C2/CT-10 should be added to the list of proposed prognostic tumor progression markers, including MUC1, AZGP1, EZH2, E2F3, Ki67, and CD10." (PMID 21754986, 2011). "Moreover, the abundance of EZH2 molecules induces the formation of more repressor complexes and, by altering the balance between different PcG components, may lead to the formation of tumor-specific PRC complexes that show differential substrate specificities." (PMID 21609503, 2011). "Taken together these results, we believe that the simultaneous induction of STEAP- and EZH2-specific CD4 and CD8 T-cell responses would be more effective in achieving anti-tumor effects than the separate induction of CD4, or CD8 T-cell responses." (PMID 22053850, 2011). "Targeting EZH2-H3K27me3 by DZNep would presumably synergize with HDAC inhibitors and/or Aza to maximally restore the tumor suppressor function of CDKN1C." (PMID 19340297, 2009). "Because we found different expression patterns for EZH2 and BMI1 in the normal mammary gland, it is possible that the expression levels we detected in the tumours are a reflection of BMI1 and EZH2 expression in the cell of origin." (PMID 19099573, 2008). "Although there does not seem to be absolute incompatibility between high levels of BMI1 and EZH2, tumours with high BMI1 have only about half the chance to have high EZH2 compared with tumours with low BMI1 (odds ratio (OR) = 0.55, p = 0.0166)." (PMID 19099573, 2008). "Further understanding the dual canonical and non-canonical roles of EZH2 in tumor biology will be key to optimizing targeted and combinatorial treatment strategies." (PMID 42257802, 2026). "ERG-driven EZH2 upregulation promotes epigenetic reprogramming and the activation of oncogenic pathways, including IGFR, MEK, WNT, NFκB, and PI3K/AKT, that facilitate tumor progression and metastasis." (PMID 41601922, 2026). "Multi-omics studies integrated subtyping, tumor-origin hypotheses, and immune landscape characterization, supporting biomarkers such as IDH2, NEUROD1, and EZH2, and highlighting heterogeneity." (PMID 42209957, 2026). "Among histone‐modifying drugs, EZH2 inhibitors like GSK126 enhance natural killer (NK) cell activity in HCC, while dual inhibitors like CM272 (targeting DNMT1 and G9a) improve tumor suppressor gene activation while reducing tumor proliferation." (PMID 40693828, 2025). "Beyond T-cell modulation, EZH2 inhibition also enhances the cytotoxic activity of natural killer (NK) cells by upregulating activating ligands, such as NKG2D ligands, thereby bolstering innate immune responses against the tumor." (PMID 40057667, 2025). "EZH2 functions as an active constituent of the PRC2 and is responsible for histone H3 lysine 27 trimethylation (H3K27me3), leading to transcriptional silencing of numerous genes, including certain tumour suppressor genes." (PMID 39779467, 2025).
tumor (continued). "After an initial growth phase of about 5 weeks, Nude-Foxn1nu/nu hosts were further treated with TM to assure efficient recombination of target genes, upon which tumor growth of the Wnt GOF group was decreased, while tumors of Ctrl and Ezh2 GOF groups remained unaffected." (PMID 41063628, 2025). "After describing the individual roles of the ferroptosis-related genes (G6PD, KIF20A, EZH2, NT5DC2, SLC7A11), it is essential to investigate how these genes might interact with each other to influence the tumor microenvironment (TME) in a synergistic manner." (PMID 40465746, 2025). "Prognostic genes including EZH2, PCNA, and BIRC5 were specifically expressed in epithelial clusters, while CHMP4C, ATP13A2, and ALDOA showed broader expression patterns, supporting their tumor-specific roles." (PMID 40678068, 2025). "In IDH-mutant gliomas, IDH mutations promote histone methylation marks including H3K27me3 by epigenetic reprogramming Meanwhile, in SHH-MB, EZH2-mediated H3K27me3 marks accumulate at NEUROD1 regulatory elements, suppressing NEUROD1 expression and maintaining tumor cells in an undifferentiated state." (PMID 40599851, 2025). "Indeed, the inhibition of EZH2 decreases FOXP3 expression on Treg cells, mitigating their immunosuppressive activity and promoting the recruitment of CD8+ T cells within the tumor microenvironment." (PMID 40554927, 2025). "Consistent with our in vitro studies, stable reconstitution of Ezh2, but not Ezh2 F667I or ΔSET mutant, largely abrogated the tumor-suppressive effects by the targeted Usp22 inhibition." (PMID 41252204, 2025). "Upon AR pathway inhibition, there may be a consequent up-regulation of PSMA; however, if the tumor undergoes neuroendocrine differentiation (NED), driven by factors like N-Myc and EZH2, epigenetic silencing of FOLH1 results in PSMA-low or -negative subclones." (PMID 40806607, 2025). "Tazemetostat and Belinostat targeting EZH2 and HDAC simultaneously affect the immunogenicity of GC-DLBC.Inhibition of EZH2 by SHR2554 and HDAC by Chidamide demonstrated combinational anti-tumor action in DLBCL as they lessen DNA replication procedures inclusive of ORC1." (PMID 39951437, 2025). "Blocking EZH2 in combination with stimulating the STING immune pathway may reverse immune resistance in SCLC models by increasing T-cell activity and tumor recognition." (PMID 41194225, 2025). "These methylation alterations may influence T cell differentiation and metabolic pathways, suggesting that EZH2 expression is regulated by epigenetic mechanisms during HCC progression and may play a critical role in tumor development." (PMID 41209556, 2025). "Understanding the connection between EZH2 and NRP1 and how their interaction drives tumor growth and therapeutic resistance through autophagy regulation could provide novel insights for therapeutic strategies." (PMID 40314246, 2025). "Additionally, EBNA3C interacts with histone methyltransferases like EZH2, a component of PRC2, depositing H3K27me3 at tumor suppressor loci." (PMID 40589575, 2025). "For example, hypoxic conditions in the tumor core inhibit TET DNA demethylases, leading to hypermethylation of pro-apoptotic genes; conversely, EZH2 overexpression in the invasive edge stabilizes a mesenchymal phenotype that enhances motility and radiation evasion." (PMID 41234540, 2025). "Also, EZH2 silences CXCL9 and CXCL10, which are T-cell recruitment chemokines, further contributing to a T-cell-excluded tumor microenvironment." (PMID 40299416, 2025). "Otherwise, the number of EZH2-positive cells in tumors was significantly similarly lowered with 50 μM TMZ or VPA–NaDCA treatment, while 3 mM NaDCA did not affect EZH2 expression in the T98G tumor." (PMID 40725030, 2025). "Thus, the interaction patterns between EZH2 and MYC, as well as the mechanisms by which EZH2 promotes the stabilization of the EZH‐MYC complex, vary across tumor types and warrant thorough investigation." (PMID 39823459, 2025).
tumor (continued). "Additionally, this RNA can interact with enhancer of zeste homolog 2 (EZH2), affecting the expression of genes involved in epithelial-to-mesenchymal transition (EMT) and tumor metastasis." (PMID 41323778, 2025). "These exosomal miRNAs act as tumor suppressors by inhibiting growth, migration, and invasion of tumor cells, as well as elevating apoptosis via targeting the FOXP4 transcription factor and EZH2 histone methyl transferase." (PMID 39805813, 2025). "Notably, EZH2 enhanced the neuropilin-1 (NRP1) level by binding to the NRP1 promoter, thereby promoting tumor proliferation and irinotecan resistance through autophagy inhibition." (PMID 40314246, 2025). "Among key epigenetic regulators, Ezh2, a histone methyltransferase and a central component of the Polycomb Repressive Complex 2 (PRC2), has been shown to drive tumour progression through H3K27 trimethylation (H3K27me3)-mediated transcriptional repression of tumour suppressor genes." (PMID 40182023, 2025). "Preclinical studies demonstrate that EZH2 inhibitors, tazemetostat and valemetostat, upregulate antigen HLA class I/II presentation machinery, OX40L, CD80 co-stimulatory ligands, and T cell-attracting chemokines, CXCL9 and CXCL10 in tumor cells." (PMID 41029427, 2025). "Our data thus far demonstrate that USP22 protects EZH2, a known negative regulator of MHC-I expression, from ubiquitination-mediated proteasomal degradation, suggesting that USP22 promotes tumor evasion of CD8+ T cell antitumor immunity through potentiating EZH2-mediated MHC-I downregulation." (PMID 41252204, 2025). "Similar to that of Usp22-targeted deletion, treatment of tumor cells with USP22i-S02 led to a substantial reduction in EZH2, but not EED, EZH1, and SUZ12." (PMID 41252204, 2025). "Moreover, in vivo findings demonstrated that PPI triggers inhibition of tumour growth, HOTAIR and the protein expressions of DNMT1 and EZH2." (PMID 40387409, 2025). "Targeting transcription factors (e.g., STAT3, AR, and Nrf2) or epigenetic regulators (e.g., EZH2 and PRMT) could facilitate a strategy that induces ferroptosis while simultaneously inhibiting tumor-promoting immunity." (PMID 41438466, 2025). "Given that EZH2 is a key component of PRC2, targeting EZH2 has been proposed as a means to disrupt the cooperative action of PRC1 and PRC2, potentially restoring the tumor‐suppressive function of BAP1." (PMID 40904706, 2025). "Collectively, our data propose that EZH2 could serve as a meaningful independent prognostic biomarker for HCC, regulated by stage-dependent epigenetic changes that may drive tumor progression by modulating immune response and cellular metabolism." (PMID 41209556, 2025). "Indeed, both the recruitment of EZH2 to the promoter regions of B2m and H2Kb and their H3K27me3 modification levels, was decreased in USP22-null tumor cells." (PMID 41252204, 2025). "EZH2 has been involved in the tumor progression mechanisms of a variety of cancer types, whereas KDM6A and KDM6B have been identified in numerous malignancies with either oncogenic or tumor suppressor roles." (PMID 41085408, 2025). "Finally, common among these two lists were the tumour suppressor genes DOK2 and PHLPP1 that demonstrated increased gene expression in response to dual inhibition of EZH2 and DNMTs in MM cells and lower expression in MM patient plasma cells compared to NPCs." (PMID 40866476, 2025). "The interaction between ANXA2 and EZH2 in cellular senescence and pyroptosis merits further investigation, as ANXA2’s pro-inflammatory effects may influence tumor therapy responses." (PMID 40018411, 2025). "For instance, EZH2 inhibition in patient samples, mouse models, and human SCLC cell lines activates the PRC2-mediated MHC-I antigen processing pathway, restoring T-cell-mediated tumor immunity." (PMID 41220942, 2025).
tumor (continued). "Studies show that downregulating EZH2 activates Nuclear Receptor Coactivator 4 (NCOA4) to trigger ferroptosis in cancer and enhances antitumor immunity by promoting CD8 + T cell infiltration into tumor tissues." (PMID 41326356, 2025). "Notably, EZH2-mediated histone methylation at the CIITA promoter represses tsMHC-II induction, thereby impairing antigen presentation and tumor immune recognition." (PMID 41359051, 2025). "It has been previously demonstrated the inhibition of EZH2, MLL1, and G9a may be a strategy to impair the survival of various tumor types, underscoring their significance as critical therapeutic targets in cancer." (PMID 39860204, 2025). "It is worth noting that inhibiting EZH2 may lead to resistance to EGFR-TKIs in NSCLC,136 and impact the tumor microenvironment, enhancing anti-tumor immunity." (PMID 40083325, 2025). "Previous patient sequencing data have indicated that EZH2 may lead to the aberrant activation of MYCN in PTCL, thereby contributing to tumor progression." (PMID 40659662, 2025). "Because tumor progression in these models involves a shift from AR-positive CRPC to AR-negative NEPC, we propose that EZH2 and PI3K/mTOR inhibitor co-treatment is particularly effective in castrate conditions due to EZH2 inhibition restoring AR expression and function." (PMID 40832297, 2025). "In PCa, coordinated expression of EZH2 and NSD2 is found to promote tumor progression." (PMID 39917394, 2025). "As a core enzyme in epigenetic regulation, Enhancer of zeste homolog 2 (EZH2) serves as a pivotal node linking epigenetic regulation, tumorigenesis, immune control, and ferroptosis, providing novel therapeutic insights for anti-tumor immunity." (PMID 41326356, 2025). "Previous studies established that the epigenetic modifier EZH2, which mediates H3K27 trimethylation and heterochromatin formation, can specifically repress the expression of Cxcl9 and Cxcl10 in several tumor entities, leading to the exclusion of cytotoxic T cells and NK cells from the TME29,30." (PMID 40562773, 2025). "To further delineate underlying molecular mechanisms by which USP22 specifically controls EZH2 protein expression in tumor cells, we first determined whether USP22 interacts with EZH2." (PMID 41252204, 2025). "Specifically, downregulation of transcription factors and subsequent decrease in miR-126 levels leads to increased expression of HOTAIR, EZH2, and DNMT1, thus impairing the epigenetic control of genes involved in differentiation, development, and tumor suppression." (PMID 40141248, 2025). "Similarly, EZH2 is a key catalytic component of PRC2, responsible for H3K27 trimethylation, which silences tumor suppressor genes." (PMID 40074445, 2025). "Our results demonstrate that the efficacy of dEZH2 with or without aPD1 in promoting EZH2 degradation and inhibiting tumor proliferation is also evident in a mouse model." (PMID 40308579, 2025). "Cell surface staining of MHC-I expression on tumor cells indicated that overexpression of Ezh2, but not Ezh2 F667I or ΔSET mutant, in Usp22-null cells impaired MHC-I expression." (PMID 41252204, 2025). "The recognition of EZH2, EGF, and AKT1 as pivotal toxicological targets in PCBs-mediated breast carcinogenesis provides critical insights into the molecular pathways through which PCBs facilitate tumor progression." (PMID 40584614, 2025). "Through unsupervised clustering of tumor cells from the scRNA-seq datasets, we identified the distinct subtype (MS1) of human SCLC characterized by CRACDlow, EZH2-mediated gene repression, and MHC-I pathway suppression, distinguished from MS2, with CRACDhigh and a functional MHC-I pathway." (PMID 41353272, 2025). "NGS of this tumor specimen was again negative for BRAF, KIT, NF1, and NRAS mutations, but was again notable for a missense mutation in EZH2 (c.2075 C > T, p.A692V)." (PMID 39984702, 2025).